MUC1 (mucin 1, cell surface associated)
Diseases named in the same sentence as MUC1 in open-access papers (continued):
Sharing a sentence is not in itself a finding about the gene and the disease.
cancer (continued). "We demonstrated that introduction of human MUC1 into the IL-10 knockout mouse accelerated the occurrence of IBD, induced a more severe grade of inflammation, and promoted cancer development and progression in over 80% of the mice." (PMID 27754373, 2016). "KL-6 mucin, one kind of MUC1, has also been investigated, and it appears to have a significant relationship with malignant tumor behavior, especially cancer cell invasion and metastasis in various gastrointestinal cancers." (PMID 26451373, 2015). "Imaging probes with aptamers are designed based on their specificity against cellular proteins, such as nucleolin, integrins and cancer biomarkers, such as PSMA and MUC1." (PMID 28536411, 2015). "Immunization of mice with the 4’F-TF-MUC1-TTox conjugate resulted in strong immune responses overriding the natural tolerance against MUC1 and producing selective IgG antibodies that are cross-reactive with native MUC1 epitopes on MCF-7 human cancer cells." (PMID 25670999, 2015). "An anti-cancer drug, Paclitaxel (PTX), was encapsulated with PLGA and conjugated with aptamers that target the MUC1 biomarker." (PMID 28536411, 2015). "By inspecting the human exitron list, we found that EIS affects several cancer-related genes: the cancer marker genes BMI1, KRT5, and MUC1 and the genes involved in cell adhesion (CSF1), migration and metastasis (ZEB2 and KLF17)." (PMID 25934563, 2015). "In parallel, we determined its potential co-expression with two cancer markers; carcinoembryonic antigen (CEA) and mucin-1 (MUC1; epithelial membrane antigen, cancer antigen CA 15–3)." (PMID 24911657, 2014). "We also showed that three mucin genes (MUC1, MUC2 and MUC4) expression in cancer cell line was regulated by DNA methylation." (PMID 24714692, 2014). "In most tissues, prominin-1 was partially co-expressed with two cancer markers: carcinoembryonic antigen (CEA) and mucin-1 (MUC1)." (PMID 24911657, 2014). "MUC1 (pan-epithelial membrane mucin), the first cloned mucin, is an important human tumor antigen, second only to WT1 in cancer antigen pilot prioritization using a ranking based on predefined and preweighted criteria." (PMID 24714692, 2014). "We have also found that the methylation status, mRNA expression, and mucin core protein expression were well correlated with each other for MUC1, MUC2, and MUC4 in cancer cell lines." (PMID 24714692, 2014). "Possible counter receptors for these interactions are CD43 and MUC1, two known ligands for ICAM-1 which are expressed by these cancer cells." (PMID 24857933, 2014). "A new anti-cancer vaccine, BLP25 liposome vaccine (Stimuvax), can identify and destroy the cancer antigen MUC1, thereby inducing an immune response against cancer cells." (PMID 25076949, 2014). "We propose that this leads to an increased interaction between MUC1 and CIN85 and thus an increase in the number of MUC1/CIN85 complexes that can promote the invasive activity of cancer cells." (PMID 24072600, 2013). "Initially we tried to establish MUC1 and MUC16 ZFN KOs of the cancer cells, but difficulties in generating the ZFN MUC1 and MUC16 KO cells prevented us from using this approach (data not shown)." (PMID 24039759, 2013). "Staining of MUC1 (membrane), HIF1A (cytoplasm), and NKX2-1 (nucleus) classified cancer by subtype and cancer-free lung tissue with a failure rate of 11.0%." (PMID 23028920, 2012). "In support of this concept, the NCI has identified MUC1 and MSLN among the most promising targets for cancer vaccine development, with the former protein listed in the top three." (PMID 22792233, 2012). "To explore the in vitro cancer targeting of the Apt-NPs against the MUC1-overexpressing cells, we compared the cellular uptake of MCF-7 (MUC1+) and HepG2 (MUC1−) using FCM analysis." (PMID 21912664, 2011). "For instance, mucins such as MUC1 and MUC4 present on cancer cells participate in signal transduction pathways that contribute to the invasive and metastatic activities of adenocarcinomas." (PMID 21283832, 2011).
cancer (continued). "The mucin 1 (MUC1) oncoprotein is a highly O-glycosylated heterodimeric, type-I transmembrane glycoprotein that is over-expressed in many cancers." (PMID 21966455, 2011). "Mucin 1 (MUC1) is a heterodimeric glycoprotein that is aberrantly overexpressed by human breast and other carcinomas." (PMID 22140559, 2011). "The PanIN3 stage, previously named in situ carcinoma, is characterized by a strong expression of MUC4 and MUC1 and occurrence of MUC3." (PMID 24281201, 2010). "Since MAL2 is known to be amplified and overexpressed in breast and other cancers, it is striking that MAL2 has now been shown to bind two proteins, MUC1 and D52, which are also amplified and/or overexpressed." (PMID 19175940, 2009). "MUC1 and MUC13, for instance, are highly expressed in such carcinomas when compared to normal colon cells." (PMID 21152207, 2009). "And in all cases, the expression of MUC1, MUC6 and 45M1 apomucins was found in the cell membranes of many carcinoma cells and the cytoplasms of some carcinoma cells." (PMID 16018800, 2005). "Using the MAb C595, we found MUC1 expression on the surface of CAPAN-1, CFPAC-1 and PANC-1 cancer cells by flow cytometric analysis and confocal microscopy." (PMID 15599383, 2004). "Another study developed a multi-epitope vaccine targeting important cancer antigens like STAT3, HER2, and GRB7 using a multimodal strategy that included MHC I, MHC II, CTL, and B-cell epitopes created from MAGE-A3, EGF, and MUC-1 by in silico immunoinformatics techniques." (PMID 40453095, 2025). "In addition to playing an important role in the field of cancer biomarkers, MUC1, promoting PDAC carcinogenesis, represents a good therapeutic target for new opportunities for cancer treatment." (PMID 40001578, 2025). "Although these studies have been conducted in cancer cells exhibiting high MUC1 expression, non-cancerous cells in contact with bacteria also show the increased expression of this gene." (PMID 40699655, 2025). "However, dysregulation in mucin expressions, such as MUC1, MUC2, MUC4, MUC5AC, and MUC16, have been observed in many cancer cells." (PMID 40699805, 2025). "More recent polymer‐based detection studies have shown either negative, or limited prognostic significance of MUC1 only in mismatch repair–proficient cancers." (PMID 41332218, 2025). "Higher cytoplasmic MUC1 expression independently predicted worse cancer-specific survival (multivariable HR for high vs. negative to low expression, 2.14; 95% CI: 1.26–3.64)." (PMID 39966658, 2025). "Eleven months after the initiation of spIND therapy, the investigational human adenovirus serotype 5 (hAd5) vector-based cancer vaccines ETBX-051 (targeting carcinogenic embryonic antigen; CEA) and -061 (targeting mucin-1; MUC1) were added, and treatment with gemcitabine/nab-paclitaxel ceased." (PMID 39373598, 2025). "MUC1 and MUC4 have consistently been shown to be highly expressed in cancer." (PMID 41011627, 2025). "It was found that S2.2 conjugation enhanced in vitro drug delivery and cytotoxicity in MUC1 overexpressing cancer cells when compared to nonspecific NPs." (PMID 41471303, 2025). "Conversely, membranous MUC1 in nodal metastases showed no prognostic impact (all carcinoma cells p = 0.125, MIPs p = 0.228, cribriform p = 0.209, and solid p = 0.187)." (PMID 41332218, 2025). "The long non-coding RNA X-inactive specific transcript (lncRNA XIST) and MUC1 gene are dysregulated in chronic inflammation and cancer; however, there is no known interaction of their functions." (PMID 38740827, 2024). "One limitation of this study is the lack of in vivo data showing that high-MUC1 cancer cells respond better to Napabucasin treatment compared to isogenic low MUC1 cells." (PMID 38326371, 2024). "Therefore, we investigated the clinical significance of MUC1, MUC2, MUC5AC, and MUC6 expression in AoV cancer." (PMID 38893239, 2024).
cancer (continued). "Interestingly, we identified a cell subpopulation defined as cancer stem cells with a transcriptomic phenotype similar to ECCs and CA-MSCs (EPCAM, MUC1, PROM121, ALDH1A3)." (PMID 38182756, 2024). "Aberrant glycosylation of MUC1 plays a role in cancer development and progression.The effect of C1GALT1 on MUC1 glycosylation plays a role in CRC development, and cancer therapies targeting MUC1 show potential, suggesting a potential effect of C1GALT1 on MUC1 glycosylation." (PMID 38699634, 2024). "Accumulating clinical results suggest that major advances, such as the incorporation of DCs pulsed with WT1 and/or MUC1 peptide vaccines and standard anticancer therapies into the clinician’s therapeutic arsenal, can prolong OS and/or PFS in many patients with cancer." (PMID 38336778, 2024). "The MUC1/estrogen receptor axis is eventually essential for cancer stem-like features, specifically in HER2-negative cells, and promotes the capability of cancer cells to form mammospheres and express stem-related genes, also reducing their sensitivity to tamoxifen administration." (PMID 39349458, 2024). "Likewise, muc1-Bi-1 and muc1-Bi-2, two bs-Abs, have demonstrated remarkable efficacy in specifically targeting MUC-1 on cancer cells and connecting it to CD16 on NK cells." (PMID 39609700, 2024). "Additionally, the enzyme's relationship with MUC1, a mucin protein with abnormal glycosylation in CRC, highlights its role in cancer cell immune evasion and metastasis." (PMID 38699634, 2024). "Evidence supports that ICAM1 binds to MUC1, which is known to be overexpressed in cancer cells and cancer stem cells, and CD80 binds to CTLA4, which is an immunosuppressive marker that is also expressed in cancer stem cells." (PMID 38903193, 2024). "To determine whether MUC1 plays a role in STAT3’s sensitivity to Napabucasin, we treated the panel of low and high MUC1 expressing cancer cells with increasing concentrations of Napabucasin." (PMID 38326371, 2024). "For example, APOE, PLAU, CDK1 and MUC1 were significantly higher in TNBC tissues than in cancer-parasite tissues, whereas PDGFRB, RET, ROCK2, CCND1 and PPARA were significantly lower in TNBC tissues than in cancer-parasite tissues." (PMID 38329441, 2024). "In particular, MUC1 directly regulates the expression of glycolytic genes (including HK2, PFKFB2, ENO1, PGK1, PGM2, LDHA, and GLUT1) and promotes increased glucose uptake and utilization in cancer cells in a HIF-dependent manner." (PMID 38540735, 2024). "Accordingly, GKN1+ ECs, MUC1+ ECs, and VIM+ ECs were regarded as cancer cells." (PMID 39422697, 2024). "HzMUC1-MMAE is a humanized MUC-1 monoclonal antibody conjugated with monomethyl auristatin (MMAE, microtubule polymerization inhibitor) designed to target BC, as MUC-1 is overexpressed in a variety of cancers, and is a marker for anti-HER2 resistance." (PMID 39123362, 2024). "MUC1 is a transmembrane protein with well-known oncogenic functions in PDAC and is known to impart transcriptional alterations that lead to metabolic reprogramming in cancer cells." (PMID 38547055, 2024). "Interestingly, MUC1 is itself a target of HIF-1α, suggesting the operation of a positive feedback loop in cancer cells under hypoxia." (PMID 36899934, 2023). "The nanoparticles upon interaction with MUC1 release PTX and induce cancer cell death." (PMID 36850121, 2023). "Galectin-3 has been shown to co-express with MUC1 and promote the adhesion of the cancer cells to endothelium by exposing the small CAMs that are normally shielded." (PMID 37444377, 2023).
cancer (continued). "Moreover, MUC1-high PCs had significantly increased levels of IFNGR1, STAT1 and IRF1, which drive IFN response genes (ISGs) and chronic inflammation in cancer cells." (PMID 36835130, 2023). "Anti-MUC1 antibodies generated in the absence of cancer appear to be promoted by inflammatory events involving tissues that normally produce MUC1." (PMID 37869082, 2023). "Additionally, other autoantibodies targeting SOX2, HIF1-α, NY-ESO-1/CTAG1B, MUC1, Her2, GAL1, and GAL3 have been frequently identified in cancer patients." (PMID 37627091, 2023). "Additionally, in a NSCLC model, the combination of prostate stem cell antigen (PSCA)- and MUC1-targeting CAR-T cells synergistically eliminated PSCA+ and MUC1+ cancer cells." (PMID 36717905, 2023). "However, TGM2_v2 mediated the repression of over 20% of these cancer-related gene transcripts, among which is HSP90B1, and induced the expression of MUC1." (PMID 37160910, 2023). "Thereafter, we induced overexpression of MUC1 in ESCC cells and found it conferred to the immunosuppressive TME and growth and mobility of cells, and it protected cancer cells from radiotherapy-induced ferroptosis by inducing nuclear translocation of β-catenin." (PMID 36688997, 2023). "An example is the non-viral prophylactic cancer vaccine against MUC1, a shared tumor antigen expressed on >80% of human cancers, which was administered to healthy individuals at risk for colon cancer." (PMID 37514155, 2023). "MUC1 with the Tn epitope as a cancer marker is an antigen that is highly expressed in a form with abnormal O-glycosylation on the surface of a variety of cancer cells, but is not expressed or is expressed at low levels in normal tissues." (PMID 38269087, 2023). "MUC1, MUC2, MUC4, MUC5AC, and MUC6 are currently the most widely covered in the literature regarding their role in the progression from normal colonic tissue to cancer." (PMID 36900282, 2023). "In addition, peptides for cancer vaccinesthat target examples of overexpressed proteins are summarized, includinghuman epidermal growth factor receptor 2 (HER-2), mucin 1 (MUC1),folate receptor, and others." (PMID 35195008, 2022). "MUC1 can be another co-receptor of HER2 overexpressed in BC cells and other types of cancer." (PMID 35248049, 2022). "However, specific monoclonal antibodies against Tn or sTn-MUC1 and MUC16 glycopeptides and GD2 (dinutuximab) have been approved by the Food and Drug Administration (FDA) for their use in cancer treatment." (PMID 35454762, 2022). "Mucin-1 (MUC1), a highly O-glycosylated glycoprotein, is overexpressed in various cancer cells." (PMID 36714624, 2022). "Apart from that, cancer growth was inhibited within immunodeficient mice bearing BDC xenografts, and a new PD-1 inhibitor conjugated to anti-CD3 and anti-MUC1 bsAbs was analyzed in a Phase II RCT (NCT03524261) in advanced BRCA cases, but no further information is available." (PMID 35883508, 2022). "MUC1 (degree = 9), an epithelial membrane antigen with roles in signaling and cell-adhesion, has been just recently explored for the development of anti-MUC1 antibodies for targeted therapy of GI cancers and development of anti-cancer vaccines." (PMID 35913978, 2022). "From mechanistic investigations, we confirmed the cancer-promoting function of HILPDA and MUC1." (PMID 36439512, 2022). "Both CAR.MUC1 T cells exhibited significantly higher cytolytic activities toward MUC1+ cancer cells compared with that of nontransduced T cells." (PMID 36457849, 2022). "Contrarily, very low rates of binding and staining were associated with MUC1‐negative HepG2 and PC3 cancer cells (Fig. 2B3,B4)." (PMID 34694686, 2022).
cancer (continued). "The mAb 5E5 recognizes an immunodominant cancer-specific epitope, Tn-MUC1 (in the GSTA region), not covered by immunological tolerance in MUC1-humanized mice." (PMID 35158915, 2022). "Cytotoxicity and pro‐apoptotic activities of anti‐MUC1 nanobody on MUC1‐overexpressing cancer cell lines were significantly higher compared to the MUC1‐expressing and MUC1‐negative cell lines." (PMID 34694686, 2022). "Combining the results of this study, we speculate that MUC1-rs4072037 and ABO-rs1053878 may affect the expression level of CA153, thereby affecting the occurrence and development of cancer." (PMID 35144566, 2022). "The reason is that MUC-1 is a self-antigen, even in its specific structure on cancer cells tolerance, which does not allow the immune system to respond properly." (PMID 35000604, 2022). "MUC-1 and toll-like receptor 7 (TLR-7) peptide in a murine model of BC were tested, and this vaccine induced CTL response and antibody-dependent cellular cytotoxicity (ADCC) and improved humoral immunity against MUC-1 + cancer cells." (PMID 35000604, 2022). "MUC1 can not only mediate hypoxia-driven angiogenesis by regulating a variety of angiogenic factors; it can also stabilize and activate hypoxia inducible factor-1α (HIF-1α) to promote the metabolic reprogramming of cancer cells." (PMID 35879749, 2022). "Specifically, cancer cell line conditioned media containing exosomes and free proteins were first incubated with three different fluorescent aptamers against CD63, EpCAM and MUC1 on AuNPs (~ 9.2 nm)." (PMID 34855021, 2021). "MUC1 can also be used as a biomarker for pigeon-sensitive asthma patients and not just a negative predictor of the survival of patients with cancers of epithelial origin." (PMID 34207342, 2021). "MUC1 and MUC16 are post-translationally modified in the tumor environment to carry immune inhibitory Siglec-9 ligands, making Siglec-9 ligands inviting targets to enhance immune surveillance in cancer." (PMID 34065256, 2021). "Overexpressed MUC1 and MUC4 on the surfaces of cancer cells provide steric hindrance for the conjugation between cancer cells and cytotoxic lymphocytes, resulting in a decreased cancer cell lysis." (PMID 34681277, 2021). "Whereas the MUC1/Y splice variant is coexpressed with the splice variant MUC1/SEC in benign tumours, this is not the case in malignant tumours." (PMID 34452200, 2021). "MUC1 is also overexpressed in other epithelial cancers, and therefore serum samples would only indicate cancer presence but not organ of origin." (PMID 34439139, 2021). "EPCAM, EGFR, and MUC1 glycoproteins are overexpressed only on the surface of epithelial cancer cells, not on cancer cells with mesodermal and ectodermal origins." (PMID 34679012, 2021). "Therefore, antigens such as β-catenin, MUC1, EGFR, FGFR, and PDGFR are sufficient targeted therapies for metastatic cancer cells, while E-cadherin is efficient for cancers in primary stages or after metastasis." (PMID 34679012, 2021). "We also observed a positive staining with anti-MUC1 antibody of the in vitro cultured endometrial cells, from the cancer and noncancerous group." (PMID 33922995, 2021). "MUC1-014E also recognized isolated cancer cells of signet-ring cell carcinoma (sig) and non-solid type poorly differentiated stomach adenocarcinoma (por2)." (PMID 33167508, 2020). "The MUC1‐related Tn, TF, STn, and STF TACAs, expressed in more than 90% of primary adenocarcinomas, are considered pancarcinoma antigens and have been widely used to design cancer vaccines." (PMID 32594569, 2020).